BCL2 (BCL2 apoptosis regulator)
Diseases named in the same sentence as BCL2 in open-access papers (continued):
Sharing a sentence is not in itself a finding about the gene and the disease.
diffuse large B-cell lymphoma (continued). "Using a Burkitt lymphoma-like gene expression signature, we recently defined a high-risk molecular high-grade (MHG) group mainly within germinal centre B-cell like diffuse large B-cell lymphomas (GCB-DLBCL), which was enriched for MYC/BCL2 double-hit (MYC/BCL2-DH)." (PMID 31844144, 2020). "A para-aortic LN biopsy revealed transformation to diffuse large B-cell lymphoma (DLBCL) with CD10 +, ki-67 proliferation index >90%, C-MYC >50%, FISH showing BCL2+, BCL6+, and MYC +." (PMID 41306534, 2025). "Gene expression profiling of germinal center B-cell diffuse large B-cell lymphoma can identify a double hit-like signature and inferior outcomes, but only half of these cases have structural rearrangements that can be detected by routine MYC and BCL2 break-apart FISH." (PMID 38903717, 2024). "Quantitative multiplexed microscopy reveals that a subpopulation of cells that coexpress MYC and BCL2 without BCL6 govern clinical outcomes in diffuse large B-cell lymphoma, underscoring the importance of analyzing protein coexpression patterns at single-cell resolution." (PMID 37071673, 2023). "The B-cell lymphoma-2 (BCL-2) inhibitor exhibited promising clinical activity in AML, acute lymphoblastic leukemia (ALL) and diffuse large B-cell lymphoma (DLBCL) treatment." (PMID 35794605, 2022). "Postoperative pathology revealed diffuse large B-cell lymphoma (DLBCL), with immunohistochemically related positive indicators, including CD20, CD79a, LCA, MUM-1, PAX5, C-MYC, BCL-2, and BCL-6, in all patients." (PMID 35734472, 2022). "In treatment-naive diffuse large B-cell lymphoma (DLBCL) patients, venetoclax, in combination with standard immunochemotherapy (R-CHOP), improved PFS, especially in the BCL2-positive (i.e., detectable by immunohistochemistry (IHC)) subgroup." (PMID 34576319, 2021). "Immunohistochemical staining on 35th day showed positive markers for CD20, EBER, BCL-2, PAX5, MUM-1 and a Ki-67 rate of 70%, which was consistent with a diagnosis of diffuse large B-cell lymphoma (DLBCL)." (PMID 31906982, 2020). "This is exemplified by diffuse large B-cell lymphoma (DLBCL) where MCL-1 contributes to intrinsic and acquired resistance to the rationally designed polyselective BCL-2, BCL-XL, and BCL-W inhibitor ABT-737 and the monoselective BCL-2 inhibitor ABT-199." (PMID 31692812, 2019). "Herein we report a case of secondary CD20-negative diffuse large B-cell lymphoma (DLBCL) coexpressing MYC and BCL-2, which originated in middle ear." (PMID 30985716, 2019). "This is because most of what we know about DHLs is based on cases with MYC/BCL2 DHL, which has an inferior prognosis when treated with regimens for diffuse large B-cell lymphoma (DLBCL) and has a very high recurrence rate with a reported median survival of only 0.2 to 1.5 years." (PMID 30323893, 2018). "The cells were negative for anti-cytokeratin, CD3, and CD10 antibodies but positive for CD20, bcl2, and MUM1 antibodies, indicating a diffuse large B-Cell malignant lymphoma (DLBCL) with a non-germinal center phenotype." (PMID 40162139, 2025). "In terms of clinical advantages, Bcl-2 inhibitors have been shown to be uniquely safe and well established in the treatment of hematologic malignancies such as chronic lymphocytic leukemia (CLL), diffuse large B-cell lymphoma (DLBCL), mantle cell lymphoma (MCL), and follicular lymphoma (FL)." (PMID 40216744, 2025). "The third pathological investigation revealed non-germinal center B cell like (GCB) diffuse large B cell lymphoma (DLBCL) with invasion of striated muscle tissue, positive for Bcl-2 (90%+), Bcl-6 (60%+), CD20 (3+), Ki67 (80%+), MUM1 (80%+) and c-myc (50%+)." (PMID 40406106, 2025). "In situ and ex vivo analysis featured such tumours as activated type of diffuse large B cell lymphoma (ABC-DLBCL), expressing BCL2 and c-MYC, but not BCL6, with activated STAT3 signaling." (PMID 36503430, 2022).
diffuse large B-cell lymphoma (continued). "When we focused on diffuse large B cell lymphomas (DLBCL), representing the largest group of cell lines, the presence of MYC or BCL2 or the cell of origin did not affect the response to PQR620." (PMID 31167506, 2019). "Double expression of MYC and BCL2 proteins (DE) and double-hit MYC+BCL2/BCL6 translocations (DH) were established as important biomarkers in patients with diffuse large B-cell lymphoma (DLBCL) by the 2016 revision of the World Health Organization classification of lymphoid neoplasms." (PMID 29088292, 2017). "Though it has been discovered that BCL2 and BCL6 proteins have an impact on diffuse large B-cell lymphoma development and outcome, they may not be good prognostic markers." (PMID 23289441, 2013). "Intriguingly, within diffuse large B-cell lymphoma (DLBCL), MNDA expression is more prevalent in the non-germinal center B-cell (non-GCB) subtype and the BCL2/MYC double-expression group, displaying a correlation with CD5 expression—a finding that merits further exploration." (PMID 40386782, 2025). "Biopsy and pathology analysis revealed a diffuse large B-cell lymphoma (DLBCL), with positive staining for CD20, CD79a, BCL2 and BLC6, but negative for CD10; 30% of the cells were positive for MIB-1 but MUM1 (IRF4) staining was negative, suggesting a germinal center-type lymphoma." (PMID 39110273, 2024).
multiple myeloma (249 papers, 2002 to 2026). "For instance, it has been reported that high levels of BCL-2 expression were associated with increased sensitivity to ABT-199 in multiple myeloma (MM), but those cells were resistant when BCL-xL or MCL-1 were also expressed." (PMID 39497108, 2024). "For the mitochondria-targeted BCL-2 inhibitor venetoclax, clinical trials have revealed that secondary resistance can arise in multiple myeloma patients who have undergone long-term venetoclax therapy or possess missense mutations in BCL-2 and BAX." (PMID 39273093, 2024). "In myeloma, the sensitivity of cells to venetoclax is strongly associated with the t translocation, since it more likely presents with high BCL2 expression and low MCL1 or BCL-XL expression." (PMID 35799216, 2022). "High levels of Bcl-2 promote cell survival and tumorigenesis and have been associated with poor outcomes and resistance to traditional anti-myeloma agents; therefore, Bcl-2 represents an attractive target for novel therapies." (PMID 36077618, 2022). "MicroRNA-497 was found to inhibit myeloma growth and increase susceptibility to bortezomib by targeting Bcl-2." (PMID 33971811, 2021). "That Bcl-2 plays an important role in the efficacy of DEX was confirmed in a study with myeloma cells where Bcl-2 overexpression was associated with resistance to DEX." (PMID 32033410, 2020). "According to the literature data, increased levels of the antiapoptotic BCL-2 protein have been associated with resistance to cytotoxic drugs and advanced stages of multiple myeloma." (PMID 29690619, 2018). "Overexpression of anti-apoptotic molecules such as Bcl-2 and Bcl-xL has been linked to chemoresistance in myeloma." (PMID 29113343, 2017). "FACS analysis of CD45−CD38+CD138+ cells showed that BDA-366 treatment at concentrations of 0.25 or 0.5μM indeed induced BCL2 conformational change in primary myeloma cells from patients, and caused the exposure of the BH3 domain." (PMID 27049723, 2016). "Bortezomib requires caspase-8 and caspase-9, whereas marizomib induces the apoptotic effect mainly through caspase-8 signaling that allows it to overcome the resistance of myeloma cells conferred by Bcl-2 mutations." (PMID 26579531, 2015). "The upregulation of BCL2 is the hallmark of resistance to apoptosis for myeloma cells." (PMID 35982976, 2022). "Furthermore, Bcl-2 is proved to associate with resistance to paclitaxel in multiple myeloma cells, which may relate to its influence on paclitaxel-induced apoptosis." (PMID 37956212, 2023). "This study demonstrated that the BCL2 inhibitor, venetoclax, is effective against myeloma cells under hypoxic conditions." (PMID 40539846, 2025). "As a selective BCL-2 inhibitor, venetoclax can induce apoptosis in myeloma cells, with those harboring t translocation exhibiting particular sensitivity to venetoclax." (PMID 40697383, 2025). "aims to assess the safety and effectiveness of ZN-d5, a novel and selective BCL-2 inhibitor, in R/R AL amyloidosis patients." (PMID 40190562, 2025). "Nevertheless, the optimal timing, patient selection, and treatment context for BCL-2–targeted therapy in AL amyloidosis remains unresolved." (PMID 41428272, 2025). "Another study indicates miR-497 as a regulator of multiple myeloma cell growth and sensitivity to bortezomib, by the regulation of BCL2." (PMID 38038871, 2024). "The intricate interplay between anti-apoptotic (e.g., Bcl-2, Bcl-xL, Mcl-1) and pro-apoptotic (e.g., Bax, Bak, Bim, Puma, Bid, Noxa) proteins governs the apoptotic death of myeloma cells." (PMID 39411073, 2024). "In a xenograft mouse model of multiple myeloma and BCL‐2, ABT‐263 exhibited increased toxicity when mice were treated with the BCL‐2, BCL‐XL, and BCL‐W inhibitor ABT‐263." (PMID 38831635, 2024). "In summary, through these integrative analyses, 16 myeloma essential genes (including BCL2) were found to be targeted by p52 bound enhancers showing increased activity in NF-κB+ samples." (PMID 38514625, 2024).
multiple myeloma (continued). "In Mcl-1-expressing myeloma cells, Bim distribution dictates Mcl-1 dependency or codependence with Bcl-2/Bcl-xL." (PMID 39411073, 2024). "Overexpression of Bcl-2 has been shown to inhibit apoptosis of plasma cells, and Bcl-2 inhibitors have demonstrated efficacy in the treatment of certain tumor diseases characterized by over proliferation of plasma cells, such as multiple myeloma." (PMID 39148739, 2024). "In AL amyloidosis, plasma cells are more susceptible to apoptosis and appear to be particularly dependent on the anti-apoptotic proteins MCL-1 and BCL2." (PMID 39020041, 2024). "The expression of Bcl-2, a key anti-apoptotic protein and the molecular target of venetoclax, has emerged as an important predictor of therapeutic response to venetoclax in myeloma patients." (PMID 38025905, 2023). "Further investigation into the relationship between genetic subtypes and Bcl-2 expression patterns holds great promise for refining patient selection strategies and optimizing the efficacy of venetoclax in the management of multiple myeloma." (PMID 38025905, 2023). "Among these therapeutic advancements, the selective Bcl-2 inhibitor venetoclax has emerged as a promising avenue, demonstrating notable efficacy in multiple myeloma patients." (PMID 38025905, 2023). "Bcl-2 and Mcl-1 proteins play a role in multiple myeloma (MM) cell survival, for which targeted inhibitors are being developed." (PMID 36672426, 2023). "BDA-366, a Bcl-2-BH4 domain antagonist, can induce conformations to change in the exposure of the BH3 domain and abrogate the anti-apoptotic function of Bcl-2, and further inhibit tumor growth of lung cancer and multiple myeloma." (PMID 37237269, 2023). "Multiple myeloma is a very heterogeneous pathology, which is also manifested by its diverse addiction to the three main anti-apoptotic molecules such as BCL2, BCLXL and MCL1 for survival." (PMID 37534243, 2023). "By directly antagonizing BCL-2’s anti-apoptotic action, Venetoclax reinstates the natural cellular process of apoptosis, particularly in cells like Multiple Myeloma cells that have aberrant BCL-2 expression." (PMID 38026941, 2023). "Preclinical data from myeloma cell lines have suggested synergism when combining a GSI with a novel BH3 mimetic (ABT-737) known to block BCL2/BCLXL to induce apoptosis." (PMID 37712875, 2023). "In this review, we delineate the mechanisms by which Venetoclax (VTC) modulates apoptosis in Multiple Myeloma (MM) cells, emphasizing its interaction with the BCL-2 protein." (PMID 38026941, 2023). "BCL2 family members are highly expressed in AL amyloidosis compared with MM, underpinning the therapeutic potential of BCL2 inhibitors in this disease." (PMID 36694297, 2023). "The study highlights the post‐transcriptional regulation in AL‐amyloidosis and provides pathogenetic evidence for the potential use of BCL‐2 inhibitors in this disease." (PMID 36694297, 2023). "Specifically, BCL2L1, MCL1, and BCL2 were upregulated in AL‐amyloidosis compared with MM and controls." (PMID 36694297, 2023). "Since miRNAs regulate gene expression we used the bioinformatics tools IPA, miRTarBase, and TargetsScan, to explore a connection between the downregulated miRNAs in AL amyloidosis and the BCL2, BCL2L1, and MCL1 genes." (PMID 36694297, 2023). "Clonal plasma cells in multiple myeloma have been found to be sensitive to inhibition of BCL-2 and MCL-1 at initial diagnosis, with increased MCL-1 dependence in relapsed disease, yet the heterogeneity in these dependencies has hampered treatment progress." (PMID 36184661, 2022). "In contrast, only 20% of myelomas favor signals through the BCL2 protein, which is a target of venetoclax." (PMID 35982976, 2022). "In multiple myeloma cells, aspirin inhibited tumor cell proliferation and induced apoptosis by upregulating Bax and downregulating Bcl-2, changing the ratio of Bax/Bcl-2." (PMID 36245983, 2022).
multiple myeloma (continued). "Since myeloma cells overexpress anti-apoptotic proteins in a heterogeneous manner, a subset of myeloma cells overexpress B-cell lymphoma-2 (BCL-2) and provide an attractive therapeutic target for BCL-2 inhibitors, such as venetoclax." (PMID 35322025, 2022). "MSC-derived EVs (MSC-EVs) have been found to contain lncRNA LINC00461 and, on uptake by multiple myeloma cells, it relieved the inhibitory effect of miR-15a/miR-16 on Bcl-2, therefore suppressing apoptosis and promoting myeloma proliferation." (PMID 35454774, 2022). "Targeting Bcl-xL in addition to Bcl-2 is a viable therapeutic strategy, as increased levels of Bcl-XL have been observed in a myeloma xenograft model that was resistant to venetoclax." (PMID 35884390, 2022). "Several other Bcl-2 inhibitors are in clinical development, as are inhibitors of Mcl-1, a Bcl-2-family oncoprotein that is perhaps more critical for myeloma cell survival than Bcl-2." (PMID 35884390, 2022). "For example, multiple myeloma is characterized by the overexpression of the anti-apoptotic proteins Bcl‐2 or Mcl-1 which favors cancer cell resistance to chemotherapy." (PMID 35965519, 2022). "Correlative analysis revealed that oblimersen sodium downregulated Bcl-2 protein levels in peripheral blood-circulating myeloma cells, as well as B cells, T cells, and monocytes." (PMID 35884390, 2022). "BAFF and APRIL stimulate multiple myeloma cells through anti-apoptotic molecules such as BCL2, MCL1." (PMID 35144648, 2022). "The combination of venetoclax or BCL2 inhibitors with other anti-myeloma drugs or novel intervention strategies has the potential to improve clinical outcomes." (PMID 35982976, 2022). "Strikingly, in mice bearing AL amyloidosis cell line xenografts, single agent treatment with the BCL-2 inhibitor ABT-199 (venetoclax) produces deeper remissions than bortezomib and triples median survival." (PMID 36184661, 2022). "Looking forward, a first-in-human phase 1 study of novel BCL-2 inhibitor lisaftoclax is underway in multiple myeloma and other hematologic malignancies with doses up to 1200 mg/day thus far being well-tolerated (NCT03537482)." (PMID 35127532, 2021). "Venetoclax, an oral selective inhibitor of anti-apoptotic protein BCL-2, has become a prototypical precision drug in myeloma." (PMID 35127532, 2021). "Anti-cancer drugs such as the pan-Bcl-2 inhibitor obatoclax (OBX) have been shown to strongly stimulate BiP translocation to the cell membrane in multiple myeloma (MM) cells." (PMID 34440849, 2021). "We next investigated the response of the CD138+ plasma cell samples from 35 patients, to five anti-myeloma therapies: Bortezomib (PI), Lenolidomide (IMiD), Navitoclax (BCL-2 inhibitor), Quizinostat (HDACi) and the investigational drug PF-04691502." (PMID 34145309, 2021). "Bcl-2 is probably a critical survival factor for myeloma cells in the hypo-proliferative early stages of the disease since it seems to lose its importance in the aggressive proliferative phase of the disease." (PMID 33923357, 2021). "This short‐term and reproducible assay can provide a quick response profile for both BCL‐2 and dual targeting and mitigate the difficulty in culturing primary myeloma cells for long periods ex vivo." (PMID 35846088, 2021). "Overexpression of BCL-2 in a subset of myeloma cells with BCL-2 survival dependency, therefore, provides an attractive therapeutic target." (PMID 34073976, 2021). "For instance, the Bcl-2 inhibitor venetoclax has been shown to inhibit mitochondrial respiration, although it appears to have higher cytotoxicity in myeloma plasma cells with reduced mitochondrial respiration." (PMID 33916196, 2021).